BCL2 (BCL2 apoptosis regulator)
Diseases named in the same sentence as BCL2 in open-access papers (continued):
Sharing a sentence is not in itself a finding about the gene and the disease.
tumor (continued). "On the other hand, the odds ratios for associating high BCL-2 expression (as compared to low BCL-2 expression) with cancer grade and tumor stage were; OR 1.170; 95% CI 0.512–2.676 and OR 1.533; 95% CI 0.746–3.149 respectively." (PMID 31289309, 2019). "These “Bcl2-rescued” NK cells undergo a functional switch from tumor-suppressive to tumor-promoting cells, since loss of STAT5 determines upregulation of the pro-angiogenic factor VEGFA, which sustains tumor growth." (PMID 31681330, 2019). "MCL1 is known to play an important role in regulating the sensitivity of tumor cells to BCL2 inhibitors as MCL1 overexpression is associated with resistance to ABT199." (PMID 31752970, 2019). "Low Bcl-2 expression was significantly associated with higher tumor stage and showed favourable prognosis." (PMID 31754362, 2019). "This suggests a survival advantage of low RGS2 expressing tumour cells by the BCL-2 associated prevention of hypoxia-induced cell-death." (PMID 30467386, 2018). "The tumor cells were also susceptible to apoptosis under VU treatment, which was revealed by activation of caspase-8/9/3 via cleaving and disruption of the Bcl-2/Bax expression balance." (PMID 29867331, 2018). "Activated STAT3 has been reported to prevent tumor cell apoptosis by regulating associated genes, such as Bcl-2, Bcl-xL and Fas." (PMID 30594131, 2018). "The correlation between BCL2 with AR-FL and AR-V7rv in PCa suggests an association between the AR-mediated pathways and the antiapoptotic process involved in tumor development." (PMID 30028845, 2018). "From this discussion it can be inferred that a higher expression of Bax, Bak, Bim, or Bad is likely to confer tumor cells a survival advantage, whereas an increased expression of Bcl-2, Bcl-xL, or Mcl-1 is likely to be associated with a poorer prognosis." (PMID 30486451, 2018). "Consistent with a pro-tumour role, mutation or deletion of pro-survival BCL2 proteins was also infrequent." (PMID 29769323, 2018). "Furtermore, BCL2 methylation levels were significantly associated not only with disease stage, but also with tumor grade." (PMID 29706891, 2018). "p62 has also been associated with tumor cell proliferation, survival, and the expression of anti-apoptotic genes like Bcl-2 and Bcl-xL." (PMID 30486451, 2018). "SBA-15|EO3 causes inhibition of tumor cell proliferation and triggers apoptosis, connected with caspase activation, upregulation of Bax, as well as Bcl-2 and Bim downregulation along with amplification of poly-(ADP-ribose)-polymerase (PARP) cleavage fragment." (PMID 29757198, 2018). "This new class of Bcl-2 inhibitor reduces thrombocytopenia risk associated with the inhibition of Blc-X while conferring a rapid reduction of tumour in CLL patients." (PMID 30134553, 2018). "Here we identified a DCIS sub-population of niche-associated tumor cells, adjacent to myoepithelial cells and BM, that are resistant to lapatinib and induce BCL2 post treatment." (PMID 28649658, 2017). "Immunohistochemical analysis demonstrated that the inhibition of tumor growth and metastasis was associated with activation of Bax, cleaved caspases-3 and -9, and down-regulation of Bcl-2, MMP-2 and -9, NF-κB and IκBα." (PMID 28751740, 2017).
tumor (continued). "Our study showed that dA increased the activation of caspase-9/3 and PARP, upregulated the Bax/Bcl-2 ratio, and caused DNA damage, suggesting that the tumour death trigged by dA was related to mitochondria associated apoptotic pathway." (PMID 28775302, 2017). "To further confirm that nifuroxazide-induced tumor cell death was associated with apoptosis, we analyzed the levels of Bcl-2, Bax and cleaved caspase-3 in CT26 cells treated with nifuroxazide using western blot." (PMID 28055016, 2017). "Bcl-2 and Twist1 overexpression was associated with a poor pathological grade and tumor prognosis, and the two factors functions as a complex." (PMID 28032603, 2017). "In subgroup analyses stratified by tumor stage and hormonal treatment, the association of BCL2 CC genotype with OS seemed to be strongest in the subgroup tumor stage –2 with hormonal treatment." (PMID 28396899, 2017). "NF-κB upregulates the expression of numerous genes implicated in facilitating tumor cell survival, such as Bcl-2, c-IAP1, and survivin." (PMID 28933726, 2017). "In conclusion, lonchocarpin significantly inhibits tumor growth both in vitro and in vivo and its underlying mechanism of action involves Bcl-2 inhibiting induced Caspase-3 activation." (PMID 28878321, 2017). "Other published targets, linked to an involvement in the regulation of apoptosis and tumour invasion, include BCL2, CDC25A and TNFAIP2." (PMID 28736583, 2017). "The BCL2 CC genotype was significantly associated with OS in the subgroup tumor stage 1–2 with hormonal treatment (HR 3.08, 95% CI 1.64–5.76; p < 0.001)." (PMID 28396899, 2017). "Hypermethylation of TERT and BCL2 was associated with tumour grading, and BCL2 was associated with tumour stage." (PMID 29038612, 2017). "It activates pro-inflammatory genes (COX-2, iNOS, TNF-α, IL-1, and IL-6) in tumor and tumor-associated cells and surrounding tissue, as well as antiapoptotic (Bcl-2, Bcl-X) and proangiogenic molecules (vascular endothelial growth factor)." (PMID 28487844, 2017). "An imbalance between Bax and Bcl-2 has been linked to the development and progression of tumours through the resistance of apoptosis." (PMID 27586579, 2016). "The anti-tumor drug actinomycin D caused less cell death and caspase-3/7 activation in Bcl-2-, Mcl-1- or Bcl-xL-overexpressing cells than in cells expressing the empty vector." (PMID 26758417, 2016). "The findings also indicated that the plasma caused apoptosis in the tumor cells through the activation of the p-53 and Bax/Bcl-2 proteins." (PMID 27383714, 2016). "Oncogenic mutations in the Bcl-2 gene that inhibit apoptosis can lead to tumor initiation, progression, or metastasis." (PMID 27223299, 2016). "An increasing number of a diverse class of small molecule inhibitors (SMIs) of Bcl-2 can be specifically used for their therapeutic potential by inducing synthetic lethality in tumor cells with other oncogenic driver mutations." (PMID 28025559, 2016). "For this purpose, we choose a siRNA for Bcl-2, the first anti-death gene discovered, implicated in tumor progression." (PMID 27886088, 2016). "An emerging strategy for cancer therapy is to overcome the resistance to apoptosis caused by aberrant Bcl-2 signaling in tumor cells." (PMID 26758417, 2016). "When tested in a phase 1 trial for adult CLL, ABT-199 showed remarkable tumor killing effects, causing overwhelming tumor lysis due to its potent on target disruption of Bcl-2 and its binding partners." (PMID 26874859, 2016). "Contrary to this data, studies have demonstrated that overexpression of Bcl-2 (anti-apoptotic) in hepatocytes or loss of Bid (pro-apoptotic) in liver carcinogenesis can actually be inhibitive to tumor progression." (PMID 28025559, 2016).
tumor (continued). "Bcl-2 is associated with tumor development; specifically, Bcl-2 expression inhibits the morphological changes during cell apoptosis, including plasma membrane blebbing, DNA cleavage and nuclear condensation, and negatively regulates cell death." (PMID 25816073, 2015). "An evidently high percentage of tumor cells expressed Bcl-2 in the control group, while apogossypol treatment caused a significant decrease in Bcl-2 expression levels in tumor tissues, indicating that apogossypol induced apoptosis in the LNCaP xenograft tumor." (PMID 25672487, 2015). "miR-15 and miR-16 act as putative tumor suppressors and target the genes such as Bcl-2 and VEGF that are implicated in regulation of cell cycle, apoptosis and proliferation." (PMID 26551008, 2015). "For TN tumors, a poorer DMFS was associated with larger tumor size (>20 mm), axillary nodal involvement, Trio and BCL2 phenotypes." (PMID 26405647, 2015). "Support for this idea comes from a study indicating that the presence of the phosphorylated form of Bcl-2 (pBcl-2-S70, phosphorylated at Serine 70) was linked to tumor regression and patients with favorable outcomes." (PMID 25826088, 2015). "The importance of this interaction is underlined by the fact that Beclin-1 is a tumour suppressor protein and that inhibition of its function by Bcl-2 contributes to the oncogenic potential of Bcl-2." (PMID 26474854, 2015). "For TN tumors, larger tumor size [HR = 2.5 (1.2–5.3), P = 0.02], nodal involvement [HR = 3.5 (1.6–7.6), P = 0.002], Trio [HR = 2.4 (1.1–5.1), P = 0.03], and BCL2 [HR = 3.3 (1.3–8.4), P = 0.01] phenotypes were associated with poorer DMFS." (PMID 26405647, 2015). "Bcl-2 is a central apoptotic inhibitor, and overexpression is associated with tumor progression and treatment resistance in cancers." (PMID 25566506, 2014). "For instance, an anti-apoptotic factor Bcl-2 is overexpressed in the tumors of 35–50% of cancer patients, but heavy-ion irradiation can overcome tumor radioresistance caused by such Bcl-2 overexpression." (PMID 25426641, 2014). "Bcl-2, Bax and survivin are molecules associated with the proliferation and apoptosis of tumor cells." (PMID 25298750, 2014). "Bcl-2 antagonizes the induction of tumor cell apoptosis, but it is also associated with tumor differentiation and longer disease-free survival." (PMID 24824621, 2014). "Of the three ER associated GATA3 targets identified above, BCL2 has the best characterized tumor-promoting activity, while DACH1 has been reported to function as both tumor promoter and tumor suppressor." (PMID 25410484, 2014). "The in vitro molecular data showed that the increase in the proliferation of tumor cells were associated with the up-regulation of Bcl-2 and survivin expressions." (PMID 25298750, 2014). "Their loss, by releasing the inhibition upon tumor-promoting genes, such as BCL2, BMI1, CCND2 and CCND1, promotes cell growth and tumor progression." (PMID 24566314, 2014). "Bcl-2 and Bcl-xL are associated with the evolutionarily conserved autophagy inducer, Beclin1, a haplo-insufficient tumor suppressor, and inhibit autophagy." (PMID 25013481, 2014). "As we reported in a recently published article, the apoptosis of tumor cells is associated with the up-regulated expressions of caspase-3 and down-regulated expressions of Bcl-2 and survivin." (PMID 23940624, 2013). "NF-κB upregulates the expression of a number of genes implicated in facilitating tumor cell survival, such as Mcl-1, Bcl-2, Bcl-XL, c-IAP1, c-IAP2, FLIP and survivin." (PMID 24146961, 2013). "Several studies have indicated that the transcription factor NF-κB regulates the expression of proteins implicated in facilitating tumor cell survival including Bcl-2, Bcl-xL, c-IAP, survivin and XIAP." (PMID 23437404, 2013).
tumor (continued). "Associated with tumor lysis, expression of the anti-apoptotic proteins Bcl-xl and Bcl-2 were markedly reduced and apoptosis increased (TUNEL assay) after nsPEF treatment." (PMID 22937117, 2012). "According to these assumptions, cancers over-expressing Bcl-2 or Bcl-XL should have worse prognosis, while tumours over-expressing Bax should be associated with better clinical outcomes." (PMID 22852863, 2012). "Given that we selectively targeted Bcl-2 and observed significant consequences on tumor-associated properties, we asked IPA to map only the downstream components of human Bcl-2-interactome known to date." (PMID 22666341, 2012). "High tumour BCL2 protein expression was associated with lower grade of tumour (p = 4 × 10-9), presence of both oestrogen and progesterone receptor in tumours (p = 1 × 10-14 and 5 × 10-5 respectively), and lack of expression of CK5/6 (p = 0.002)." (PMID 23961365, 2012). "RB produced a profound inhibition of PARP, Bcl-2, and Bcl-xL expressions in tumor tissues from treated mouse groups, whereas caused a striking increase in the expression of Bax, consistent with the results in culture cells." (PMID 22666431, 2012). "Our study suggested that NF-κB participated in the formation of tumor resistance via multidrug resistance encoding protein P-gp and Bcl-2, with Bax that existed in mitochondrial apoptosis pathway." (PMID 22159556, 2012). "Multiple chemotherapies cause an additional increase in mdr1b and bcl-2 gene expression in RLS40 cells that makes the tumor less sensitive to cytostatic treatment." (PMID 23251817, 2012). "In several studies, over-expression (Cyclin D1, NF-κB, PCNA) or loss of expression (Bcl-2) of these markers have been found to correlate with more aggressive tumor growth in CRC." (PMID 23133595, 2012). "The proto-oncogene Bcl2 encodes an inner mitochondrial protein that reportedly antagonizes apoptosis in many tumor cells." (PMID 19383839, 2011). "In HT1080 cells, AKAP12 was found to suppress tumor cell viability by inducing apoptosis via caspase-3 and was associated with a decreased expression of Bcl-2 and increased expression of Bax." (PMID 21918680, 2011). "BCL-2 expression has been seen in less aggressive tumor behavior and is linked to increased cell survival." (PMID 21776270, 2011). "We also assessed the expression of other NF-κB–regulated genes Bcl-2, Bax and Cyclin B1, the overexpression of which have been linked to tumor survival, apoptosis and cell cycle arrest." (PMID 21901145, 2011). "In the present study, the expression of bax was associated with that of bcl-2, and bax overexpression correlated significantly with some clinicopathological features such as gender, histological type, Borrmann type, tumor location, and lymph node metastasis." (PMID 22216342, 2011). "One of the genes bound solely from the cancer biopsy extract was found to encode Bcl2, which is known to be down-regulated by AP2α to provoke tumor cell apoptosis upon chemotherapy." (PMID 21876733, 2011). "Overexpression of BCL-2 or BCL-XL not only leads to resistance to apoptosis but has also been linked to increased tumour cell motility." (PMID 20515495, 2010). "Multivariate Cox proportional hazards regression analysis was performed to derive risk estimates related to survival for age, gender, stage, tumor differentiation, histological type and Bcl-2 expression; cases with missing values were excluded from analysis." (PMID 20459695, 2010). "Bcl-2 is implicated in cancer development, tumor progression and protection of cells from a wide range of cytotoxic insults, including cytokine deprivation, irradiation, and chemotherapeutic drugs." (PMID 21304176, 2010).
tumor (continued). "Activated STAT3 has been shown to protect tumour cells from apoptosis by regulating genes encoding antiapoptosis-associated proteins, such as Bcl-2, Bcl-xl, and Mcl-1." (PMID 20461084, 2010). "Bcl-2 gene expression is associated with aggressive tumor behavior in response to chemo- and radiotherapy." (PMID 22649602, 2009). "We identified that CD44+/CD133+ MiaPaCa2 cells are enriched with tumorsphere-forming and tumor-initiating cells or cancer stem/progenitor cells with high levels of Notch/Bcl-2 and loss of miR-34." (PMID 19714243, 2009). "We have also identified that CD44+/CD133+ MiaPaCa2 cells are enriched with tumorsphere-forming and tumor-initiating cells or CSC with high levels of Notch/Bcl-2 and loss of miR-34s." (PMID 19714243, 2009). "The oncogene Bcl-2 is classically associated with follicular lymphomas and appears to be associated with chemoresistance in these types of tumours." (PMID 18380893, 2008). "The susceptibility of tumor cells to the induction of apoptosis by chemotherapeutic agents is controlled by the ratio of Bcl-2/Bax proteins in the mitochondria." (PMID 17407577, 2007). "We investigated the effects of inhibiting the Bcl-2 antiapoptosis oncoprotein on the susceptibility of Bcl-2-overexpressing tumour cells to cytotoxic immune cells." (PMID 17311012, 2007). "Antisense oligonucleotides that decrease Bcl-2 expression caused direct tumour suppression and increased sensitivity to cytotoxic chemotherapy in preclinical models." (PMID 17311012, 2007). "The overexpression of proapoptotic factors, eg Mcl-1, bcl-2 or bcl-xL, has been implicated in cancer development, tumour progression and therapy resistance of B-cell lymphoproliferative diseases." (PMID 17473827, 2007). "Radioresistant tumours were associated with expression of the antiapoptotic markers bcl-2 and bcl-XL and underexpression of the proapoptotic marker bax." (PMID 15928664, 2005). "Since Bcl-2 is maximally elevated in the tumour lines and induced in the normal line, the action of l-deprenyl cannot be solely associated with a Bcl-2-related antiapoptosis effect." (PMID 14612913, 2003). "The mechanism underlying the effect of Bcl-2 oncoprotein expression on tumour progression and prognosis remains essentially uncertain." (PMID 12838300, 2003). "A direct association between VEGF and tumour size (P=0.001) as well as between PgR and bcl-2 (P=0.001) were present only in IDC." (PMID 12402149, 2002). "High levels of Bcl-2 are preferentially expressed in well-differentiated tumours and are associated with favourable prognosis." (PMID 8679463, 1996). "In tumour tissues with stable silencing of circKIAA1797, the expression levels of the proliferation-associated protein Ki67, the cycle-associated protein Cyclin D1, the migration-associated protein RhoA and the apoptosis-associated protein Bcl2 were reduced." (PMID 40176113, 2025). "Moreover, the expression of genes associated with apoptosis (Bax and Bcl2) and inflammation (Il6 and IL1b) in tumor tissues was notably modulated by rapamycin." (PMID 40361560, 2025). "Curcumin can directly induce the loss of mitochondrial membrane potential in tumor cells by modulating the Bax/Bcl-2 ratio and inhibiting the ATP-sensitive potassium channel (mitoKATP) located on the mitochondrial membrane, consequently triggering mitochondria-dependent apoptosis." (PMID 41515171, 2025). "In addition, IGF1 upregulates the expression of the anti-apoptotic proteins Bcl-2, Bcl-XL, and survivin, thus promoting a drug-resistant tumor cell phenotype associated with metastatic hMM." (PMID 40724880, 2025). "Also, a higher serum BCL2 level was associated with advanced cancer grade and pathologic tumor status." (PMID 40730640, 2025).